CDKN2A (cyclin dependent kinase inhibitor 2A)
Diseases named in the same sentence as CDKN2A in open-access papers (continued):
Sharing a sentence is not in itself a finding about the gene and the disease.
pancreatic cancer (continued). "The proportion of tumors with elevated CDKN2A expression is higher in breast cancer (8%) and pancreatic cancer (6.1%), but remains low." (PMID 36765923, 2023). "There is some evidence of activity of these drugs in other tumors harboring CDKN2A aberrations, like pancreatic cancer and non-small cell lung cancer." (PMID 37998367, 2023). "A 20‐year pancreatic cancer surveillance study of 347 CDKN2A PGV carriers identified 36 PDAC cases in 31 (8.9%) individuals through annual magnetic resonance imaging." (PMID 36999792, 2023). "In the 14 studies analysed, CDKN2A was significantly higher in patients with pancreatic cancer then in healthy controls (OR 17.2, p < 0.00001), however the low sensitivity (41%) and positive predictive value (58%) make it an unsuitable diagnostic biomarker." (PMID 37460806, 2023). "In pancreatic cancer, a series of SVs, including large deletions, inversions, and translocations, led to the inactivation of CDKN2A/p16 and SMAD4/DPC4." (PMID 37674481, 2023). "We present a cohort with a large number of CDKN2A heterozygotes under surveillance, in which an early pancreatic cancer was detected and a curative treatment was offered." (PMID 36980574, 2023). "It has been found to be frequently co-deleted with the neighboring tumor suppressor gene CDKN2A (which codes p16-INK4a and p14ARF) in various tumors, and its deletion has been reported in a significantly high proportion in pancreatic cancer." (PMID 38203561, 2023). "The first tumor suppressor gene described in pancreatic cancer as inactivated by aberrant hypermethylation in its promoter was CDKN2A/p16INK4, which plays a crucial role in inhibiting cell cycle progression the G1 to S phase, ensuring cell cycle arrest." (PMID 37798621, 2023). "Single mutations were identified in MEN1 for gastric cancer, MSH6 for colorectal cancer, CDKN2A for pancreatic cancer, and EPCAM/TSC2/GALNT12 for breast cancer." (PMID 38201513, 2023). "Considering the relationship between aging, invasion, and metastasis of pancreatic cancer, it is crucial to consider ITGA2 mutation as significant as CDKN2A, BRCA1/2, and PALB2 mutations in the diagnosis and treatment of pancreatic cancer." (PMID 37881431, 2023). "21CDKN2B deletion is considered essential for pancreatic cancer development instead of co-deletion with CDKN2A." (PMID 38024139, 2023).
pancreatic cancer (continued). "Coding for tumor suppressors p16 and p14 (ARF) which regulate the cell cycle, patients with germline mutation in the CDKN2A gene have a high risk of developing melanoma, glioblastoma, and pancreatic carcinoma." (PMID 38076247, 2023). "For CDKN2A PV carriers, these guidelines recommend initiation of surveillance 10 years earlier than the earliest age of pancreatic cancer diagnosis in the family, or at age 40, whichever is earlier." (PMID 35372037, 2022). "CDKN2A is involved in cell-cycle progression and has been validated to play an important role in many kinds of cancers, including pancreatic cancer, sebaceous gland carcinoma of the eyelid and so on." (PMID 36247012, 2022). "Therefore, CDKN2A VUSs may play a significant, unappreciated role in risk of pancreatic cancer." (PMID 35001868, 2022). "Mutations in the CDKN2A gene, which are linked to the familial atypical multiple mole-melanoma (FAMMM) syndrome, are associated with a 13- to 22-fold increased risk of pancreatic cancer." (PMID 35626055, 2022). "On the provider level, pancreatic cancer surveillance for individuals with CDKN2A PVs has been increasingly endorsed by expert consensus, although the efficacy of these surveillance methods remains under study." (PMID 35372037, 2022). "For this reason, expert consensus has recommended pancreatic cancer surveillance for all individuals with CDKN2A PVs." (PMID 35372037, 2022). "In some pancreatic cancers, tumor suppressor or DNA repair genes (such as CDKN2A, CDH1 and MLH1) are found to be silenced by methylation." (PMID 36173644, 2022).
pancreatic cancer (continued). "The first is termed hereditary pancreatic cancer, which occurs in individuals with a known hereditary cancer syndrome caused by germline single gene mutations (e.g., BRCA1/2, CDKN2A)." (PMID 35761384, 2022). "In pancreatic carcinoma, one of the most aggressive (severe) human tumors, CDKN2A expression is significantly reduced in about 95% of cases." (PMID 35456025, 2022). "CDKN2A is a major susceptibility gene for familial atypical multiple mole melanoma syndrome (FAMMM), and FAMMM kindreds are at high risk of developing pancreatic cancer." (PMID 34476650, 2021). "The CDKN2A methylation frequency is significantly higher in pancreatic cancer patients, which is related to patient survival." (PMID 35004697, 2021). "P16/CDKN2A and oncogenic K-Ras expression co-exist alongside other aging markers, whereas in pancreatic cancer, the expression of P16/CDKN2A and markers are omitted." (PMID 33918146, 2021). "In pancreatic cancer, the most frequently active tumor suppressor gene is P16/CDKN2A, which blocks CDK4/6 mediated phosphorylation of retinoblastoma, which blocks entry into the S phase of the cell cycle." (PMID 33918146, 2021).
pancreatic cancer (continued). "In pancreatic cancer, CDKN2A is one of the most frequently altered genes, and its inactivation caused by loss of heterozygosity, homozygous deletion or promoter silencing has been observed in 98% of pancreatic cancer cases." (PMID 30922330, 2019). "Intense vigilance and early intervention are important, since age of diagnosis is low, especially among CDKN2A mutants, while medical advice on healthy lifestyle and prompt screening for other cancers, such as pancreatic cancer, is essential." (PMID 29774366, 2018).
pancreatic cancer (continued). "Screening is recommended for high-risk individuals, including patients with a family history of pancreatic cancer or patients with an STK11, CDKN2A/p16, or a BRCA2 mutation with ≥1 affected first-degree relative." (PMID 28283772, 2017). "There are several reports of increased risks of other cancer types in CDKN2A-families in addition to pancreatic cancer." (PMID 27804060, 2017). "Among 178 CDKN2A mutation carriers, PDAC was found in 7.3% (N = 13), 0.9% in the familial pancreatic cancer group (N = 2; 1 advanced PDAC, 1 grade 2 neuroendocrine tumour [NET]) and 1 PDAC was diagnosed among BRCA2 carriers." (PMID 29069866, 2017). "CDKN2A/p16 was one of the first recognized tumor suppressor genes to undergo hypermethylation at the promoter region and lead to gene silencing in pancreatic cancer." (PMID 28294968, 2017). "Concerning pancreatic tumors, the CDKN2A/p16INK4A gene is inactivated in 95% of invasive carcinomas, 40% by homozygous deletion, 40% by an intragenic mutation coupled with loss of the second allele and 10–15% of cases by gene promoter hypermethylation." (PMID 26884312, 2016). "There are compelling epidemiologic and molecular evidences pointing to a key role for the CDKN2A gene in pancreatic cancer etiology." (PMID 27486979, 2016).